RHOT1 (ras homolog family member T1)
Description:
Atypical mitochondrial nucleoside-triphosphatase (NTPase) involved in mitochondrial trafficking. Probably involved in control of anterograde transport of mitochondria and their subcellular distribution. Promotes mitochondrial fission during high calcium conditions. Can hydrolyze GTP, ATP and UTP.
Synonyms: MIRO-1; ARHT1; FLJ11040; MIRO1
Tractability: Small molecule: a structure with a bound ligand is known. Antibody: UniProt predicts a signal peptide or a membrane-spanning region. PROTAC: UniProt records ubiquitination sites on it; ubiquitination databases record sites on it; its protein half-life has been measured.
Gene: Protein-coding gene on chromosome 17 (32,142,442 to 32,253,374, forward strand). Ensembl gene ENSG00000126858.
Subcellular location: Mitochondrion outer membrane
Pathways (Reactome):
Metabolism of proteins: Ub-specific processing proteases
Signal Transduction: RHOT1 GTPase cycle
Gene Ontology:
Molecular function: ATP hydrolysis activity; calcium ion binding; GDP binding; GTP binding; GTPase activity; magnesium ion binding; protein binding; ribonucleoside triphosphate phosphatase activity
Biological process: cellular homeostasis; mitochondrial outer membrane permeabilization; mitochondrion transport along microtubule; regulation of mitochondrion organization; mitochondrion organization
Cellular component: membrane; mitochondrial outer membrane; mitochondrion
Genetic constraint (gnomAD): Loss-of-function variants: 17 observed, 42.59 expected, observed/expected ratio (o/e) 0.4, 90% interval 0.27 to 0.6. The upper end of that interval is the gene's LOEUF score, 0.6, which puts it in group 2 of 6, group 1 being the genes least tolerant of losing a copy. Missense variants: 316 observed, 409.52 expected, observed/expected ratio (o/e) 0.77, 90% interval 0.7 to 0.85. Synonymous variants: 112 observed, 133.15 expected, observed/expected ratio (o/e) 0.84, 90% interval 0.72 to 0.98.
Homologues: Orthologues: chimpanzee RHOT1 (99% identical), macaque RHOT1 (99% identical), pig RHOT1 (99% identical), dog RHOT1 (99% identical), guinea pig RHOT1 (99% identical), mouse Rhot1 (98% identical), rat Rnf135 (97% identical), rabbit RHOT1 (97% identical), tropical clawed frog rhot1 (86% identical), zebrafish rhot1a (81% identical), zebrafish rhot1b (79% identical). Paralogues in human: RHOT2 (56% identical), RHOBTB2 (14% identical), RHOBTB1 (13% identical), RAC1 (12% identical), RHOU (12% identical), CDC42 (11% identical), RAC2 (11% identical), RAC3 (11% identical), RHOG (11% identical), RHOV (11% identical), RHOJ (10% identical), RHOQ (10% identical), and 10 more.
Diseases named in the same sentence as RHOT1 in open-access papers:
RHOT1 is named in the same sentence as 71 diseases in open-access papers, as found by Europe PMC text mining. Sharing a sentence is not in itself a finding about the gene and the disease. The quoted sentences say what the papers report.
Parkinson disease (25 papers, 2014 to 2026). A progressive degenerative disorder of the central nervous system characterized by loss of dopamine producing neurons in the substantia nigra and the presence of Lewy bodies in the substantia nigra and locus coeruleus. "Several heterozygous RHOT1/Miro1 variants were identified in sporadic Parkinson’s disease patients." (PMID 36533136, 2022). "Mutations in genes of the mitochondrial transport machinery have been described for RHOT1 (the gene encoding Miro1 protein) and they are linked to decreased endoplasmic reticulum-mitochondrial contact sites and impaired calcium homeostasis in fibroblasts from Parkinson’s disease (PD) patients." (PMID 34805174, 2021). "Moreover, altered Miro1 protein levels have emerged as a shared feature of monogenic and sporadic Parkinson's disease (PD), but, so far, no disease-associated variants in RHOT1 have been identified." (PMID 31303019, 2019).
pancreatic cancer (9 papers, 2012 to 2024). "Low expression levels of RhoT1 appear to be significantly associated with lymph node metastasis and shorter survival in pancreatic cancer patients." (PMID 38874808, 2024). "Deregulation of RHOT1 expression may be a risk factor for pancreatic cancer in NF1 microdeletion patients, although the reported data refer to NF1 patients without distinguishing between different forms of NF1." (PMID 38874808, 2024). "RHOT1 expression is upregulated in pancreatic cancer, cholangiocarcinoma, esophageal cancer, glioblastoma, acute myeloid leukemia, thymoma, and other cancers." (PMID 38378644, 2024). "Although the function of RHOT2 in cancer is still unclear, the expression of its paralog RHOT1 affects metastasis in a variety of tumors, including pancreatic cancer, gastric cancer, small cell lung cancer, etc.." (PMID 37158593, 2023). "Jiang and Li presented that RHOT1 affected the biological behavior of pancreatic cancer by EMT phenotype." (PMID 35170374, 2022). "RHOT1 as an oncogene regulated the proliferation and migration of pancreas cancer cells via SMAD4-dependent TGF-β signaling." (PMID 35170374, 2022). "The aim of this study is to examine the relationship between the expression of RhoT1, Smad4 and p16 and metastasis and survival in patients with pancreatic cancer." (PMID 22860091, 2012). "In this study, we found that high RhoT1 expression was inversely correlated with survival of patients with pancreatic cancer (P = 0.034)." (PMID 22860091, 2012). "Further studies are clearly needed to elucidate the mechanism of RhoT1 involved in pancreatic cancer." (PMID 22860091, 2012). "Several studies have shown that the expression of RHOT1 is significantly increased in pancreatic cancer patients; siRNA-RHOT1 significantly inhibits the migration and invasion of SW1990 pancreatic cancer cells, with the mechanism mainly involving the regulation of SMAD4 expression." (PMID 38378644, 2024). "Taken together, the present study suggests that RhoT1 may be considered as a potential prognostic biomarker for overall survival, and as a potential therapeutic target for intervention in patients with pancreatic cancer." (PMID 22860091, 2012). "Moreover, the results of univariate Cox proportional hazards analysis for the cytoplasmic expression of RhoT1, Smad4 and p16 in pancreatic cancer tissues showed that the low-expression of RhoT1 was correlated with an increase in the risk of death (P = 0.042)." (PMID 22860091, 2012). "Furthermore, low cytoplasmic expressions of RhoT1 and Smad4 were associated with LNM and worse survival in patients with pancreatic cancer." (PMID 22860091, 2012). "However, so far few studies have investigated the relationship between the expression of RhoT1 and the outcome or prognosis for patients with pancreatic cancer." (PMID 22860091, 2012). "Collectively, these results suggest that RhoT1 may be a novel tumor suppressor gene of pancreatic cancer, and the low cytoplasmic expression of RhoT1 may serve as a potential predictor for the tendency to metastasize." (PMID 22860091, 2012). "RhoT1 may be considered as a potential novel marker for predicting the outcome in patients with pancreatic cancer." (PMID 22860091, 2012). "For instance, RHOT1 can regulate cell migration and proliferation by suppressing the expression of SMAD4 in pancreatic cancer." (PMID 32467664, 2020). "Therefore, we have carried out this study to examine the expression of RhoT1, Smad4 and p16 in pancreatic cancer, and to analyze whether the expression patterns of RhoT1, Smad4 and p16 are correlated with metastatic potential and are predictive of clinical outcome in patients with pancreatic cancer." (PMID 22860091, 2012). "The analysis showed that the high cytoplasmic expression levels of RhoT1, Smad4 and p16 in pancreatic cancer tissues had significantly negative correlation with lymph node metastasis (LNM) (P = 0.017, P = 0.032, P = 0.042, respectively)." (PMID 22860091, 2012).
breast carcinoma (5 papers, 2020 to 2023). "Moreover, in the case of control samples, we found overexpression of the proteins: PRDX2, PRDX5 and AIFM1 involved in ROS; TUSC2 in PMM; ALKBH7, RHOT1, SAMM50, IMMT and HSPA9 in the MMO; and FUNDC2 in MIT compared to luminal A and basal-like breast cancer tumors." (PMID 35327574, 2022).
hepatocellular carcinoma (3 papers, 2021 to 2024). A malignant tumor that arises from hepatocytes. "Circular RNA RHOT1 (hsa_circRNA_102034), which is spliced from the RHOT1 gene, plays an oncogenic role in hepatocellular carcinoma progression by initiating the expression of NR2F6 to recruit TIP60." (PMID 34926705, 2021).
lymph node metastasis (3 papers, 2012 to 2024). "Associations between the cytoplasmic expression of RhoT1, Smad4, p16 and the presence of lymph node metastasis and perineural invasion." (PMID 22860091, 2012). "The results demonstrated that the high expression of RHOT1 showed a positive correlation with lymph node metastasis (P = 0.035) and TNM staging (P = 0.042)." (PMID 35170374, 2022). "Analyzing from the staining pictures, the positive expression was predominantly in poorly differentiated GC tissues with or without Lymph node migration, also the poorer the histological differentiation or with lymph node metastasis, the stronger the RHOT1 expression." (PMID 35170374, 2022).
diabetes (2 papers, 2017 to 2023). "To find more support for the role of RHOT1 in insulin secretion and T2D, we silenced Rhot1 in β-cells and evaluated a rodent model of diabetes." (PMID 38086799, 2023). "We found an almost complete ablation of Rhot1 protein levels in islets of adult GK rats, whereas young GK rats, just developing diabetes, had intermediate levels." (PMID 38086799, 2023). "The discrepancy in insulin content between the two models may be due to that the knock-down specifically focus on the effect of RHOT1, whereas in the GK rat, Rhot1 is probably one of several factors, which together contribute to diabetes." (PMID 38086799, 2023).
thymoma (2 papers, 2022 to 2024). A neoplasm arising from the epithelial cells of the thymus. "RHOT1 gene expression can be found upregulated (pancreatic adenocarcinoma, cholangio carcinoma, esophageal carcinoma, glioblastoma or acute myeloid leukemia and thymoma) as well as downregulated (adrenocortical carcinoma, ovarian serous cystadenocarcinoma, skin cutaneous melanoma)." (PMID 35959487, 2022).
type 2 diabetes (2 papers, 2021 to 2023). "Here the authors present an epigenetic case-control study in human pancreatic islets revealing changes that contribute to type 2 diabetes development, e.g., epigenetic downregulation of RHOT1." (PMID 38086799, 2023).
colon cancer (1 paper, 2023). "As compared to control group, the expression of circ-NOL10, circ-LDLRAD3, circ-RHOT1, and CEA level in CRC, colon cancer, and rectum cancer patients was significantly upregulated (P ˂ 0.001, 0.001, 0.002), while circ-SMARCA5 was insignificantly upregulated (P = 0.233, 0.264, 0.280 respectively)." (PMID 37587156, 2023).
diabetic cardiomyopathy (1 paper, 2021). Diabetic cardiomyopathy is a disorder of the heart muscle in people with diabetes. "This review will consider how the outer mitochondrial membrane protein Miro1 (Rhot1) mediates mitochondrial movement along microtubules via crosstalk with kinesin motors and explore the evidence for molecular level changes in the setting of diabetic cardiomyopathy." (PMID 34277734, 2021).
heart failure (1 paper, 2026). Inability of the heart to pump blood at an adequate rate to meet tissue metabolic requirements. "Together, cardiomyocyte-selective loss of Rhot1/2 expression in the adult heart does not cause peripartum-associated heart failure, despite reduced cardiac energetic and contraction gene expression." (PMID 42278517, 2026).
intracranial aneurysm (1 paper, 2021). "Compared with RHOT1, IRAK3 has been revealed to be related with MAPK and NF-kappa B signaling pathway, which participate in the pathological process of intracranial aneurysm." (PMID 34336924, 2021).
non-small cell lung carcinoma (1 paper, 2022). A group of at least three distinct histological types of lung cancer, including non-small cell squamous cell carcinoma, adenocarcinoma, and large cell carcinoma. "Circ-RHOT1 overexpression abolished proliferation, migration, and invasion induced by propofol in non-small cell lung cancer by regulating miR-326." (PMID 35198554, 2022).
polyp (1 paper, 2023). A usually exophytic mass attached to the underlying tissue by a broad base or a thin stalk. "For polyp patients, there were positive correlations between circ-RHOT1 and circ-NOL10, circ-LDLRAD3, CEA (P = 0.002, 0.039, 0.043 respectively)." (PMID 37587156, 2023).
cancer (21 papers, 2012 to 2025). A tumor composed of atypical neoplastic, often pleomorphic cells that invade other tissues. "Logistic regression analysis showed that the cytoplasmic expression level of RhoT1 in cancer tissues acted as an independent risk factor for LNM (P = 0.042)." (PMID 22860091, 2012). "Two other family members, RhoC and RhoT1, present a number of published mutations in cancer samples and cell lines, with the S73 residue a hotspot in RhoC, while mutations in RhoT1 include a P30L mutation, which by homology may have similar effects to the Rac1 P29S mutation." (PMID 27104658, 2016). "Currently, the role of RHOT1 in mitochondrial localization is mostly studied in neurons, and its involvement in cancer requires further research." (PMID 38378644, 2024). "Circ-SMARCA5, circ-NOL10, circ-LDLRAD3, and circ-RHOT1 were differentially expressed in patients with CRC as well as in non-cancer patients." (PMID 37587156, 2023). "With regard to lncMB1 it is a cytoplasmic transcript, antisense to Rhot1 gene, encoding for a RAS protein involved in mitochondrial homeostasis, apoptosis and cancer." (PMID 34359754, 2021). "In agreement with previous observations 17, all the cancer associated exon-cassette events were skipped, including ES events in KRAS and RHOT1, indicating protein feature losses or changes that was frequently observed in cancer progression." (PMID 31695792, 2019). "In the present study, we found that there were significant differences of the cytoplasmic expression of RhoT1, Smad4 and p16 between cancer and paracancerous tissues." (PMID 22860091, 2012). "The cytoplasmic expression levels of RhoT1, Smad4 and p16 were lower in cancer tissues than paracancerous tissues (P<0.0001, P<0.0001, P = 0.002, respectively)." (PMID 22860091, 2012). "We found that specific clinical traits, such as cutaneous and neurodevelopmental abnormalities or cancer susceptibility, could be associated with the position effect of ZNF207 and RHOT1 downregulation, respectively." (PMID 38874808, 2024). "So far little is known about the role of RhoT1 in cancer progression." (PMID 22860091, 2012). "Therefore, we are interested in knowing whether the RhoT1 is similarly involved in the development of cancer." (PMID 22860091, 2012). "This study provides new insights into the possible implication of circ-SMARCA5, circ-NOL10, circ-LDLRAD3, circ-RHOT1 in CRC progression, where they are expressed differentially in CRC patients as well as non-cancer patients (UC, polyp, and piles)." (PMID 37587156, 2023). "The other genes (SMARCE1, DISC1, CENTD2, RHOT1, ARHGAP6, ARHGEF9 and ARHGEF11) are also involved in cancer progression or chemoresistance." (PMID 23300757, 2012). "Circ-RHOT1 may act as a target for miR-326 to indirectly control PDK2 expression and therefore affect cancer development, whereas circ-RHOT1 positively controlled PDK2 expression by sponging miR-32627." (PMID 37587156, 2023). "The analysis showed that high cytoplasmic expression level of RhoT1 was significantly negative correlation with LNM in cancer tissues (P = 0.003)." (PMID 22860091, 2012). "Genes and AS events enrolled in the comprehensive prognostic signature included RHOT1 (ES), SH3KBP1 (AP), AGTRAP (AA), PACS2 (AP), RBPMS (AT), B3GNTL1 (AP), MOBP (AT), NPHP3 (ES), ABCC5 (RI), FKTN (ES) and FKBP8 (AA), many of which are known to play important roles in cancer biology." (PMID 32467664, 2020).
tumor (15 papers, 2012 to 2026). "Interfering with RHOT1 inhibited mitochondrial dynamics, which prevented the recruitment of mitochondria to the cortical cytoskeleton of tumor cells and the results have blocked the capacities of cell invasion and migration." (PMID 35170374, 2022). "Like RhoB, high-expression of RhoT1 was negatively correlated with tumor aggressiveness." (PMID 22860091, 2012). "These coordinated interactions drive mitochondrial transfer, tumor aggressiveness, and therapy resistance, consistent with clinical data showing that high HMGB1, RHOT1, or RAC1 expression correlates with shorter overall survival in HCC patients." (PMID 41226616, 2025). "Immunohistochemistry staining revealed that RHOT1 was more localized in the cytoplasm of cells, and HCC staining was deeper compared to the matched adjacent non-tumor tissues." (PMID 38378644, 2024). "Circ-SMARCA5 and circ-NOL10 may act as tumor suppressors, while circ-LDLRAD3 and circ-RHOT1 may be oncogenes." (PMID 37587156, 2023). "In addition, previous studies have found that Myc regulation of mitochondrial trafficking through RHOT1 and RHOT2 enables tumor cell motility and metastasis." (PMID 37158593, 2023).
neurological diseases (7 papers, 2018 to 2025). "From previous studies, we could know that RHOT1 as a new member of the GTPase family exerted a few functions in nervous system diseases and tumors." (PMID 35170374, 2022).
neurodegenerative disease (6 papers, 2019 to 2026). A disorder of the central nervous system characterized by gradual and progressive loss of neural tissue and neurologic function. "To identify additional carriers of the herein described RHOT1 variants, we next searched a whole-exome database on neurodegenerative diseases containing 1500 patient genomes." (PMID 31303019, 2019). "While the classic Rho GTPases play important roles in actin cytoskeletal regulation, Miro1 (RhoT1) and Miro2 (RhoT2) are atypical Rho-like GTPases involved in modulating mitochondrial homeostasis and apoptosis and are strongly implicated in neurodegenerative diseases such as PD." (PMID 34054432, 2021).
infection (2 papers, 2024 to 2025). The state of being infected such as from the introduction of a foreign agent such as serum, vaccine, antigenic substance or organism. "As the immediate neighboring protein-coding genes, RHOT1 and LRRC37B, were not identified in this round of RNA-seq, it seems unlikely that VILMIR regulates these genes during infection." (PMID 40130878, 2025).
RHOT1 also shares sentences with these, for which no sentence is quoted: neuroblastoma (6 papers); amyotrophic lateral sclerosis (5); asthma (5); motor neuron disease (4); schizophrenia (4); melanoma (3); Parkinson (3); Stroke (3); airway hyperresponsiveness (2); Alzheimer disease (2); Anxiety (2); cardiomyopathy (2); Cognitive impairment (2); gastric cancer (2); Insulin resistance (2); neurodevelopmental disorder (2); peroxisome biogenesis disorder (2); acute myeloid leukemia (1); age (1); allergic asthma (1); Ataxia (1); atherosclerosis (1); autism spectrum disorder (1); autosomal recessive disease (1); cardiac arrest (1); Cerebral ischemia (1); cholangiocarcinoma (1); chronic lung disease (1); colorectal cancer (1); COVID-19 (1).
A further 22 diseases each share a sentence with RHOT1 in 1 paper.